GLP1R (glucagon like peptide 1 receptor)
Diseases named in the same sentence as GLP1R in open-access papers (continued):
Sharing a sentence is not in itself a finding about the gene and the disease.
atherosclerosis (59 papers, 2012 to 2026). A disease characterized by the build-up of fatty material and calcium deposition in the arterial wall resulting in partial or complete occlusion of the arterial lumen. "Studies have found that GLP-1R agonists can decrease the risk of cardiovascular disease and alleviate the progression of atherosclerosis." (PMID 39858999, 2024). "We further demonstrate Glp1r expression in atherosclerosis and plaque-associated cells, which functionally resemble macrophages but appear to be of smooth muscle origin." (PMID 35401813, 2022). "Nevertheless, precise identification of vascular GLP-1R+ cell types linked to the reduction of atherosclerosis following treatment with GLP-1RA remains uncertain." (PMID 34673572, 2021). "Randomized clinical studies have shown a reduction in cardiovascular outcomes with glucagon-like peptide 1 receptor agonist (GLP-1RA) treatment with the hypothesized mechanisms being an underlying effect on atherosclerosis." (PMID 36644202, 2022). "And Recent studies have indicated that GLP-1R signaling exerts protective effects against atherosclerosis and endothelial dysfunction, along with anti-inflammatory effects on macrophages and anti-proliferative effects on smooth muscle cells." (PMID 40230860, 2025). "All above is consistent with anti-inflammatory effect of GIPR/GLP1R agonism, which plays a role in improving atherosclerosis lesion severity." (PMID 39741663, 2024). "The protective effect of GLP-1R agonists on atherosclerosis has also been confirmed in clinical studies." (PMID 39858999, 2024). "Another study analyzing atherosclerosis-associated biomarkers in T2DM females reported a decrease in MMP2 and MMP9 levels with an increase in GLP-1 and GLP-1R levels." (PMID 37686344, 2023). "Collectively, these observations suggest that Glp1r expression occurs in atherosclerosis, but primarily in vascular smooth muscle cells." (PMID 35401813, 2022). "Glp1r expression was noted in human Type III atherosclerosis; known for a high number of de-differentiated VSMCs." (PMID 35401813, 2022). "In vitro studies and experimental animal models with GLP-1R agonists have demonstrated consistent reduction in atherosclerosis which have been theorized, at least in part, to be mediated through GLP-1R and cAMP signaling pathways." (PMID 35401813, 2022). "This benefit on atherosclerosis has resulted in the implicit assumption that the GLP-1R is expressed widely in the cardiovascular system." (PMID 35401813, 2022). "The data above provided a sound rationale for the delivery of a GLP-1R agonist Lira as an intervention in atherosclerosis with the goal of targeting cholesterol-loaded smooth muscle cells to effectively prevent smooth muscle-to-macrophage transition." (PMID 35401813, 2022). "These beneficial effects were difficult to pinpoint within atherosclerotic plaque due to lack of particular specificity of such agonists to the vascular cells and an inadequate understanding of the GLP-1R expression in atherosclerosis." (PMID 35401813, 2022). "In Apoe-/- mice liraglutide suppressed acyl-coenzyme A cholesterol acyltransferase 1 (Acat1) expression, foam cell formation and decreased atherosclerosis, and inhibited progression of early-onset atherosclerosis lesions in a GLP1R-dependent fashion." (PMID 33440821, 2021). "To further examine the protective effects of Dula against atherosclerosis, we evaluated mRNA expression levels of Glp-1r, inflammatory and coagulation markers in abdominal aorta." (PMID 33446799, 2021). "Studies of integrin β7–/– mice revealed protection from atherosclerosis, findings attributed to elevated levels of endogenous GLP-1 secondary to loss of the GLP-1R+ IEL population." (PMID 34673572, 2021). "The work described here shows that the GLP-1R agonist, liraglutide, has a direct effect on macrophage phenotype in early atherosclerosis resulting in inhibition of lesion formation in vivo." (PMID 29110715, 2017).
atherosclerosis (continued). "Since increased benefit in CV outcomes with GLP-1R agonists have now been established, investigating the effects of GLP-1R agonists on atherosclerosis-associated inflammation and determining their atheroprotective mechanism is important." (PMID 29110715, 2017). "It has previously been reported that exendin-4, a GLP-1R agonist, attenuates atherosclerosis through PKA–PI3K/Akt–eNOS–p38 MAPK–JNK- dependent pathways via a GLP-1R-dependent mechanism, without affecting metabolic parameters." (PMID 24490809, 2014). "The anti-inflammatory effect of GLP-1R activation was also reported in the animal model of atherosclerosis." (PMID 23621921, 2013). "On the other hand, GLP-1R expression in endothelial cells, vascular SMCs, monocytes, macrophages, and lymphocytes also raises the prospect for direct effects on atherosclerosis and inflammation." (PMID 22973260, 2012). "As is postulated for atherosclerosis, GLP-1R–expressing endothelial cells and/or immune cells may contribute in part to the antiinflammatory actions in both acute and semi-chronic cardiac injury." (PMID 41178710, 2025). "Previous observations in mice models of advanced macrovascular disease have claimed that treatment with the GLP-1R agonist liraglutide conferred attenuation of atherosclerosis and plaque stabilization as well as reduced vascular inflammation and oxidative stress." (PMID 38541121, 2024). "This implies that alterations in GLP-1R expression levels are a more responsive indicator than the proportional macrophage composition when considering the chronic inflammatory progression of atherosclerosis." (PMID 38136567, 2023). "Given the importance of myeloid cells in pathogenesis of atherosclerosis 13 and the previously reported expression of Glp1r in myeloid cells 14, we analyzed the levels of Glp1r mRNA transcripts in cultured primary cells derived from the bone marrow and peritoneum of Apoe-/- mice." (PMID 35401813, 2022). "Using a high fidelity polymerase and a set of primers that yields a PCR product encompassing the majority of the GLP-1R open reading frame, we analyzed Glp1r expression in the whole aorta from thirty Apoe-/- mice at different stages of atherosclerosis progression." (PMID 35401813, 2022). "Additionally, we investigated the cell-specific expression and localization of Glp1r in the atherosclerotic plaque, plaque-derived cells and cultured primary cells together with coordinate experiments in human atherosclerosis." (PMID 35401813, 2022). "Here, we hypothesized that the direct engagement of the GLP-1R in atherosclerosis by targeted agonists will alleviate vascular inflammation and plaque burden, even at a very low dose." (PMID 35401813, 2022). "In a proof-of-concept study we show that the delivery of microdoses of Glp1r agonist by means of “activatable” nanoparticles, via an engineered drug delivery vehicle enables spatially restricted and site-specific activation in atherosclerosis." (PMID 35401813, 2022). "Considering roles for GLP-1R+ cells in atherosclerosis, GLP-1R expression has been described within ECs and vascular smooth muscle cells, and within immune cell populations, with the highest levels of immune cell GLP-1R expression detected within intestinal intraepithelial lymphocytes (IELs)." (PMID 34673572, 2021). "Nevertheless, the precise GLP-1R+ cell types transducing signals leading to the reduction of atherosclerosis remain unclear." (PMID 34673572, 2021). "Recently, several studies have shown that DPP-4 inhibitors and GLP-1R agonists exert also a potent anti-inflammatory effect and thus, may potentially contribute to the prevention of atherosclerosis." (PMID 22973260, 2012). "GLP-1R agonists could alleviate the inflammation of the vascular wall in atherosclerosis." (PMID 39858999, 2024).
atherosclerosis (continued). "However, what is not clear is the proportion of this CV protective mechanism that is driven by local GLP-1R stimulation versus the cumulative peripheral effects that may indirectly improve vascular function and atherosclerosis." (PMID 37401947, 2023). "Moreover, the widespread distribution of GLP-1R in the vascular system, including endothelial cells, smooth muscle cells, and macrophages, provides further evidence for the potential direct protective effect of liraglutide against atherosclerosis." (PMID 37278349, 2023). "Importantly, de-differentiated vascular smooth muscle cells demonstrated significant Glp1r expression levels, suggesting that these could represent the cells with predominant Glp1r-positivity in atherosclerosis." (PMID 35401813, 2022). "CETP mice, a transgenic mouse model with accelerated atherosclerosis, showed that combined GIPR/GLP1R agonism attenuated the development of severe atherosclerotic lesions." (PMID 39834741, 2024). "Detection of reduced Glp1r expression in the livers of Glp1rTie2–/– mice prompted us to assess whether hepatic indices of metabolism or inflammation were differentially regulated in atherosclerosis-prone, PCSK9-AAV–treated, HFHC diet–fed mice treated with or without semaglutide." (PMID 34673572, 2021). "Many drugs, such as dipeptidyl peptidase 4 (DPP4) inhibitors, glucagon-like peptide-1 (GLP-1) receptor (GLP-1R) agonists, and sodium glucose cotransporter 2 (SGLT-2) inhibitors (SGLT-2i), also inhibit atherosclerosis development by reducing the proinflammatory response in EAT and PVAT." (PMID 40760703, 2025). "Myeloid cells (macrophages, monocytes) or endothelial cells are unlikely to be the source of the cells expressing Glp1r in atherosclerosis." (PMID 35401813, 2022). "Nevertheless, neither of these atherosclerosis-relevant in vitro conditions were able to induce Glp1r expression, even when ECs were expressing high levels of smooth muscle markers Acta2 and Cnn1." (PMID 35401813, 2022). "Although we determined that a wide range of Tie2+ ECs and HL cells are not required for the antiatherogenic actions of semaglutide, our studies did not identify the precise GLP-1R+ cells required for GLP-1RAs to attenuate atherosclerosis." (PMID 34673572, 2021). "According to a recent study, GLP-1R is mainly expressed in the macrophage enrichment region of atherosclerotic plaques, which provide us a new perspective on pharmacological modification of GLP-1R upon signal in atherosclerosis." (PMID 34131405, 2021). "In contrast to phenotypes observed in integrin β7–/– mice, Glp1rTie2–/– mice with marked reduction of IEL Glp1r expression did not exhibit any differences in circulating levels of GLP-1 or any baseline differences in atherosclerosis plaque burden." (PMID 34673572, 2021). "The present results suggest an involvement of renin gene expression in the NTN mouse independent of T2DM, chronic hypertension, and atherosclerosis, pointing to potential beneficial effects of GLP‐1R agonist treatment relevant for several forms of nephropathy." (PMID 34277961, 2021). "Recent cardiovascular outcome trials (CVOTs) have provided evidence that the Glucagon-like peptide-1 receptor agonist (GLP-1RA) is a promising hypoglycemic drug that can delay the progression of atherosclerosis and improve the prognosis of ASCVD patients." (PMID 38559688, 2024). "Hence, GLP-1R potentially serves as a mediator in the modulation of macrophage polarization and in the release of distinct inflammatory molecules via the NLRP3/Caspase1 pathway, thereby influencing the progression of atherosclerosis." (PMID 38136567, 2023). "GLP-1RAs attenuate atherosclerosis independent of the endothelial and hematopoietic Glp1r." (PMID 34673572, 2021).
atherosclerosis (continued). "There were technical limitations of this study, such as that we were not able to co-stain GLP1R, ɑSMA and CD68 in the same human atherosclerosis specimens." (PMID 35401813, 2022).
Hypertension (56 papers, 2010 to 2026). The presence of chronic increased pressure in the systemic arterial system. "In the biomarker-disease co-expression network, APOB was associated with the highest number of diseases significantly linked to OSCC, while GLP1R predicted only two diseases, including hypertensive disease, which was co-predicted by both APOB and GLP1R." (PMID 40696350, 2025). "Fifth, the risk of developing hypertension was lower in SGLT2i users than in DPP4i users even after excluding individuals with glucagon-like peptide-1 receptor agonist." (PMID 38600275, 2024). "Two DEGs associated with hypertension (Ephx2 and Glp1r) were in the list of the top 40 genes showing the highest differences in expression in ISIAH and WAG renal cortex." (PMID 26821914, 2016). "The list of the top 40 genes showing the highest differences in expression in ISIAH and WAG renal cortex contained two genes (Ephx2 and Glp1r) associated with hypertension." (PMID 26821914, 2016). "Several of them (Ace, Comt, Cyp1a1, Glp1r, Hsd11b2, and Ren) are widely known as associated with hypertension development." (PMID 26821914, 2016). "A previous study demonstrated that liraglutide increased vascular endothelial GLP-1R expression, and its expression contributed importantly to liraglutide-mediated cardiovascular protection in mice with experimental arterial hypertension." (PMID 37754815, 2023). "In conclusion, we have demonstrated that long-term central treatment with GLP-1R agonist attenuates the development of hypertension via mechanisms involving the activation of brainstem DBH neurons and suppression of sympathetic nerve activity in SHR." (PMID 31537818, 2019). "We here report that repeated lateral ventricular (LV) injection of GLP-1R agonist, liraglutide, once daily for 15 days counteracted the development of hypertension in spontaneously hypertensive rats (SHR)." (PMID 31537818, 2019). "Consequently, the chronic activation of the GLP1R partially abolished hypertension-induced adverse remodeling of the heart apparently through Akt stimulation." (PMID 38732142, 2024). "In an ATII-induced experimental hypertension mice model, GLP-1R activation in endothelial cells by liraglutide inhibited leukocyte vessel wall infiltration, resulting in lowered oxidative stress and reduced endothelial NO synthase (eNOS) uncoupling, which eventually prevented vascular remodeling." (PMID 37754815, 2023). "While GLP-1R agonists have been demonstrated to attenuate hypertension in response to high-salt load and angiotensin-II infusion in rodents, human studies suggest that GLP-1 receptor agonists can reduce circulating angiotensin-II levels in the absence of blood pressure effects." (PMID 35884965, 2022). "Glucagon-like peptide 1 receptor agonists (GLP1-RA), revolutionary drugs in term of medical management of obesity, positively impact BP in multiple ways above and beyond the expected positive effects of weight loss on hypertension." (PMID 36561082, 2022). "GLP-1R activation reduces vascular inflammation by selectively acting on endothelial cells rather than myeloid cells to reduce the cardiovascular complications of arterial hypertension." (PMID 34825006, 2021). "We have shown that the sustained GLP-1R activation in the CNS decreased the sympathetic nerve activity and counteracted hypertension, in which the activation of the AP and NTS DBH neurons could be implicated." (PMID 31537818, 2019). "The glucagon-like peptide-1 receptor (GLP-1R), is a prototypical class B GPCR involved in the regulation of glucose homeostasis, food intake, inflammation and hypertension." (PMID 39389952, 2024). "GLP-1R agonists and DPP-4 inhibitors could induce natriuresis and relieve hypertension via NHE3 downregulation or increased BNP release." (PMID 33923115, 2021).
Hypertension (continued). "Therefore, in this current study, we present the latest evidence about glucagon-like peptide-1 receptor agonists (GLP-1RA) and dipeptydilpeptidase-4 inhibitors (DPP-4i), which are a relatively newer class of antihyperglycemic agents on hypertension in the diabetic milieu." (PMID 34258291, 2021).
non-alcoholic fatty liver disease (48 papers, 2018 to 2026). "G49 is another GLP-1R/GCGR dual agonist shown to improve liver regeneration in non-alcoholic fatty liver disease." (PMID 37091864, 2023). "Studies on glucagon-like peptide-1 receptor agonists for the treatment of non-alcoholic fatty liver disease have reported promising results." (PMID 33897616, 2021). "GLP-1 receptor (GLP-1R) agonists have significant therapeutic effects on non-alcoholic fatty liver disease (NAFLD) and steatohepatitis (NASH) in animal models." (PMID 30510243, 2018). "In view of the recent interest in GLP-1R agonism as a nonalcoholic fatty liver disease treatment, we evaluated liver histology after chronic treatment, showing greater steatosis resolution with exendin-phe1." (PMID 29686402, 2018). "Efficacy of BI456906 as a treatment for non-alcoholic steatohepatitis (NASH), the most severe form of non-alcoholic fatty liver disease (NAFLD), is also expected, due to the emerging successful approach for this pathology using dual GLP-1R/GCGR agonists." (PMID 34195230, 2021). "In rats, a HF has a negative impact on GLP1-r expression, which is reduced after 3 months of feeding rats, leading to nonalcoholic steatohepatitis (NASH) and nonalcoholic fatty liver disease (NAFLD)." (PMID 28840471, 2018). "Despite the lack of GLP-1R expression, GLP-1RAs appear to have a positive effect on non-alcoholic fatty liver disease/non-alcoholic steatohepatitis (NAFLD/NASH), as evidenced by a clinical trial with liraglutide and now under further investigation in clinical trials with semaglutide." (PMID 31031702, 2019).